RNU6-937P (RNA, U6 small nuclear 937, pseudogene)
Gene: Small nuclear RNA gene on chromosome 20 (35,928,570 to 35,928,675, reverse strand). Ensembl gene ENSG00000207053.
Homologues: Orthologues: chimpanzee U6 (100% identical), macaque U6 (94% identical), guinea pig U6 (74% identical), rabbit U6 (73% identical), rat LOC120099406 (70% identical), guinea pig U6 (69% identical), pig U6 (69% identical), dog U6 (65% identical). Paralogues in human: RNU6-21P (85% identical), RNU6-936P (83% identical), RNU6-15P (82% identical), RNU6-268P (82% identical), RNU6-1 (81% identical), RNU6-1037P (81% identical), RNU6-1249P (81% identical), RNU6-144P (81% identical), RNU6-16P (81% identical), RNU6-2 (81% identical), RNU6-38P (81% identical), RNU6-3P (81% identical), and 1288 more.